TBC1D9B (TBC1 domain family member 9B)
Description:
May act as a GTPase-activating protein for Rab family protein(s).
Synonyms: KIAA0676; GRAMD9B
Tractability: Antibody: UniProt predicts a signal peptide or a membrane-spanning region; the Human Protein Atlas places it where antibodies can reach. PROTAC: ubiquitination databases record sites on it; its protein half-life has been measured.
Gene: Protein-coding gene on chromosome 5 (179,862,058 to 179,907,911, reverse strand). Ensembl gene ENSG00000197226.
Subcellular location: Membrane
Subcellular location (Human Protein Atlas): Plasma membrane; Actin filaments; Nucleoli fibrillar center; Nucleoplasm
Gene Ontology:
Molecular function: protein binding; GTPase activator activity; calcium ion binding
Biological process: regulation of cilium assembly; system process
Cellular component: membrane
Genetic constraint (gnomAD): Loss-of-function variants: 89 observed, 119.4 expected, observed/expected ratio (o/e) 0.75, 90% interval 0.63 to 0.89. The upper end of that interval is the gene's LOEUF score, 0.89, which puts it in group 3 of 6, group 1 being the genes least tolerant of losing a copy. Missense variants: 1,537 observed, 1,637.5 expected, observed/expected ratio (o/e) 0.94, 90% interval 0.9 to 0.98. Synonymous variants: 667 observed, 675.49 expected, observed/expected ratio (o/e) 0.99, 90% interval 0.93 to 1.05.
Homologues: Orthologues: macaque TBC1D9B (98% identical), chimpanzee TBC1D9B (95% identical), dog TBC1D9B (93% identical), rat Tbc1d9b (93% identical), mouse Tbc1d9b (92% identical), rabbit TBC1D9B (91% identical), guinea pig TBC1D9B (86% identical), tropical clawed frog tbc1d9b (74% identical), pig TBC1D9B (74% identical), zebrafish tbc1d9b (71% identical). Paralogues in human: TBC1D9 (64% identical), TBC1D8B (47% identical), TBC1D8 (47% identical), SGSM3 (15% identical), RABGAP1L (13% identical), RABGAP1 (12% identical), TBC1D1 (12% identical), TBC1D4 (12% identical), TBCK (12% identical), TBC1D2B (12% identical), TBC1D2 (11% identical), EVI5L (11% identical), and 33 more.
Diseases named in the same sentence as TBC1D9B in open-access papers:
TBC1D9B is named in the same sentence as 7 diseases in open-access papers, as found by Europe PMC text mining. Sharing a sentence is not in itself a finding about the gene and the disease. The quoted sentences say what the papers report.
cerebral infarction (1 paper, 2025). An ischemic condition of the brain, producing a persistent focal neurological deficit in the area of distribution of the cerebral arteries. "In MMD, the inhibition of PCTN by TBC1D9B may lead to similar pathological processes that cause cerebral infarction." (PMID 40722175, 2025).
Moyamoya disease (1 paper, 2025). Moyamoya disease (MMD) is a rare intracranial arteriopathy involving progressive stenosis of the cerebral vasculature located at the base of the brain causing transient ischemic attacks or strokes. "TBC1D9B and ARAP3 may promote the pathological development of moyamoya disease through immune response, metabolism." (PMID 40722175, 2025).
myocardial infarction (1 paper, 2019). Gross necrosis of the myocardium, as a result of interruption of the blood supply to the area, as in coronary thrombosis. "Six hub genes, including BCL3, HCK, PPIF, S100A9, SERPINA1, and TBC1D9B that differentiated on admission after myocardial infarction the HF patients from the non-HF ones, can serve as early prognostic biomarkers of post-AMI patients." (PMID 31850068, 2019).
cancer (1 paper, 2024). A tumor composed of atypical neoplastic, often pleomorphic cells that invade other tissues. "The results showed that the mRNA levels of TBC1D1, TBC1D7, TBC1D8 and TBC1D14 significantly varied between different cancer stages, whereas the mRNA levels of TBC1D9b and TBC1D25 did not." (PMID 38766486, 2024). "The functions of TBC1D9b, TBC1D14 and TBC1D25 in cancer have not been well studied but are known to be closely related to autophagy." (PMID 38766486, 2024).
infection (1 paper, 2015). The state of being infected such as from the introduction of a foreign agent such as serum, vaccine, antigenic substance or organism. "The average gene expression change from nine comparisons at 12 h and 6 h post-infection also show upregulation of TBC1D9B and a >2-fold increase in gene expression seven days post-infection." (PMID 26426037, 2015).
tumor (1 paper, 2024). "In the present study, TBC1D9b, TBC1D14 and TBC1D25 were significantly overexpressed in HCC, and the expression levels of TBC1D9b, TBC1D14 and TBC1D25 were significantly correlated with HCC tumor grade." (PMID 38766486, 2024).
TBC1D9B also shares sentences with these, for which no sentence is quoted: skin cutaneous melanoma (1 paper).